SIRT1 (sirtuin 1)
Diseases named in the same sentence as SIRT1 in open-access papers (continued):
Sharing a sentence is not in itself a finding about the gene and the disease.
cholestasis (continued). "Moreover, SIRT1 may be an effective therapeutic target for treating diseases related to cholestasis." (PMID 28553227, 2017). "18βGA treatment-controlled cholestasis activates the Sirt1/farnesoid X receptor (FXR) and Sirt1/Nrf2 signaling pathways." (PMID 36903944, 2023). "Under pathological conditions of cholestasis, toxic BAs such as (T-DCA)-, T-CA and DCA reduce the expression of sirtuin 1 (SIRT1, a transcriptional regulator of FXR) in hepatocytes." (PMID 35572649, 2022). "Taken all together, Sirt1 is involved in the activations of FXR and Nrf2, and can be a therapeutic target for the cholestasis treatment." (PMID 34630081, 2021). "In livers of chronic cholestatic liver disease patients (primary biliary cirrhosis and primary sclerosing cholangitis) and in BDL mice, SIRT1 expression is upregulated, suggesting that FXR is less acetylated during cholestasis." (PMID 34646233, 2021). "Rats with cholestasis induced by ANIT was used to evaluate the protective effects and mechanism of PF by regulating SIRT1/FXR and NF-κB/NLRP3 signaling pathway." (PMID 34512782, 2021). "The expression of Sirt1 in cholestasis varies in different studies; Sirt1 expression was unaltered in BDL mice in our study, whereas a previous study reported an increase in Sirt1 expression in liver samples from patients with cholestasis." (PMID 32701506, 2020). "In the pathological state of cholestasis, toxic bile acids such as taurodeoxycholic acid (TDCA), taurocholic acid (TCA), and DCA can reduce the expression level of SIRT1 in hepatocytes." (PMID 32765278, 2020). "It is worth noting that although the role of Sirt1 in FXR/BA metabolism has been studied intensively, its role and therapeutic implications in cholestasis are unclear." (PMID 32701506, 2020). "Therefore, we speculate that SIRT1 is a therapeutic target for the cholestasis treatment." (PMID 28553227, 2017). "Simultaneously, Sirt1 activation increases Nrf2 expression, thus leading to the basolateral efflux transporters (Mrp3, Mrp4) upregulation and thereby increasing bile efflux and ameliorating ANIT-induced cholestasis." (PMID 36012159, 2022). "Additional in vivo studies showed that the reduction, but not complete inhibition, of SIRT1 expression in liver had a therapeutic potential to improve liver parenchyma status during cholestasis." (PMID 30229970, 2019). "In summary, our work raises awareness that expression levels of SIRT1 should be considered when designing therapeutic strategies to treat cholestasis, which should aim to the attenuation, though not complete inhibition, of SIRT1." (PMID 30229970, 2019). "The aim of this study was to investigate whether oral administration of SRT1720, the activator of SIRT1, could alleviate ANIT-induced cholestasis and hepatotoxicity in mice." (PMID 28553227, 2017). "However, SIRT1’s role in cholestatic liver injury (CLI) is complex, with both SIRT1 overexpression and depletion showing potential detrimental effects, indicating its dual role in cholestasis." (PMID 40052151, 2025). "Resveratrol, a known SIRT1 activator, can counteract ANIT-induced cholestatic liver injury mainly by regulating BA homeostasis and reducing hepatic inflammation, both of which are regulated in an FXR-dependent manner, thereby contributing to amelioration of cholestasis." (PMID 34899349, 2021). "In this study, based on an assessment of the protective effect of PF on cholestatic liver injury, the effect of PF on SIRT1/FXR and NF-κB/NLRP3 inflammasome signaling pathway was further investigated, which might provide a deeper comprehension of PF for cholestasis." (PMID 34512782, 2021). "SIRT1‐overexpressing (SIRToe) and hepatocyte‐specific SIRT1‐KO (knockout) mice (SIRThep–/–) were subjected to bile duct ligation (BDL) and were fed with a 0.1% DDC (3,5‐diethoxycarbonyl‐1,4‐dihydrocollidine) diet to determine the biological relevance of SIRT1 during cholestasis." (PMID 30229970, 2019).
cholestasis (continued). "Therefore, liver SIRT1 can regulate FXR and is one of the most important factors which can influence the metabolism of hepatic bile acid, and it has been reported that SRT1720 can treat the cholesteric liver injury in a mice model of cholestasis." (PMID 28553227, 2017). "However, despite the remarkable potential of SIRT1 to modulate BA metabolism processes, the role of PTE in cholestasis has never been investigated, to the best of our knowledge." (PMID 34899349, 2021). "Although SIRT1 could modulate bile acid metabolism, it was not confirmed whether its activator could reverse ANIT-induced cholestasis and liver injury." (PMID 28553227, 2017).
COVID-19 (24 papers, 2021 to 2025). A disease caused by infection with severe acute respiratory syndrome coronavirus 2. "There is increasing evidence of SIRT1 involvement in the pathogenesis of coronavirus disease-2019 (COVID-19), the causative agent of the recent pandemic." (PMID 36139497, 2022). "NAD+ deficiency impairs SIRT1 function, modulating cytokine production; the uncontrolled production of cytokine, the so-called cytokine storm, has been related to severe symptoms of COVID-19." (PMID 36674947, 2023). "SIRT1 activators have been linked to beneficial effects on COVID-19 severity and mortality." (PMID 39086962, 2022). "Further research into the potential of SIRT1 activators in the amelioration of excessive inflammatory responses may provide a treatment strategy for the acute lung injury and cytokine storms often associated with COVID-19 pathology." (PMID 36139497, 2022). "Because extracellular HMGB1 is strongly associated with the clinical severity of COVID-19, leytragin-induced SIRT1 activation may contribute to the development of HMGB1-targeting therapeutics and thus to the prevention of the cytokine storms that often accompany COVID-19." (PMID 36139497, 2022). "Our study, to the best of our knowledge, is the first to evaluate SIRT1 expression in NK cells isolated from patients with severe COVID-19." (PMID 40927375, 2025). "In patients with COVID-19, a decrease in SIRT1 expression is paralleled by elevation of proinflammatory cytokines." (PMID 38020136, 2023). "Several proteins and enzymes are involved in the pathophysiological mechanisms of COVID-19, such as silent mating-type information regulation 2 homolog 1 (SIRT1) and phospholipase A2." (PMID 37759876, 2023). "Expression of SIRT1 mRNA, a major inhibitor of oxidative stress–induced senescence in lung endothelial and epithelial cells, was shown to be decreased in COVID-19." (PMID 37008787, 2023). "COVID-19 pathophysiology includes not only increased ROS production that leads to depletion of NAD+ but also decreased expression of SIRT1." (PMID 35456985, 2022). "Sirtuin 1 (SIRT1) activates PGC-1α through its deacetylation, and expression of SIRT1 was significantly decreased along with increased concentrations of plasma proinflammatory cytokines in peripheral blood mononuclear cells from COVID-19 patients." (PMID 35203953, 2022). "Presumably, the inhibition of SIRT1/NF-κB pathway has a therapeutic role in alleviating the severe form of COVID-19." (PMID 33669990, 2021). "In this sense, it has recently been reported that the SIRT1 protein (a class 3 HDAC) was positively regulated in the lung of patients with severe COVID-19 comorbidities." (PMID 34031419, 2021). "As a result, ongoing research has been centred on validating SIRT1 inhibitors for treating COVID-19." (PMID 34102081, 2021). "Citicoline acts as a SIRT1 activator, and by increasing its expression, concomitantly induces the neuroprotective properties of SIRT1 and beneficially in cognitive reservation and prevention of other neurologic disorders in COVID-19." (PMID 35053804, 2021).
COVID-19 (continued). "Moreover, the literature-based pathway analysis uncovered a set of specific genes, such as CALCA, ACE, SIRT1, TNF, IL6, CCL2, and others, that were found to mediate the association between OA and COVID-19." (PMID 38020136, 2023). "Similarly, previous studies have reported that downregulated SIRT1 and PGC1α were observed in COVID-19 patients." (PMID 35409008, 2022). "On the other hand, SIRT1 is an enzyme involved in COVID-19 due to its regulator NAD+." (PMID 35458574, 2022). "Seemingly, targeting PARP-1 and SIRT1 with theophylline could also be beneficial in the treatment of COVID-19 patients." (PMID 35456985, 2022). "Incidentally, SIRT1 was upregulated in the lungs of COVID-19 patients exhibiting severe symptoms." (PMID 34102081, 2021). "However, further studies are required to elucidate the precise role of SIRT1 in COVID-19." (PMID 40927375, 2025). "It has also been demonstrated that SIRT1 activators, such as cytarabine and resveratrol, may attenuate the development of cytokine storms and alleviate hyperinflammation and neuroinflammation-mediated cognitive dysfunction in COVID-19 patients." (PMID 38020136, 2023). "Therefore, when OA patients are infected with COVID-19, a preexisting state of reduced SIRT1 activity may worsen inflammation and contribute to an increase in mortality risk." (PMID 38020136, 2023). "Since SIRT1 positively affects COVID-19, its activators may be a potential adjuvants therapy." (PMID 35458574, 2022). "Finally, the known mislocation of SIRT1 and SIRT6 throughout the genome and the decline of NAD+ during aging could be major factors causing age-dependent symptoms of COVID-19." (PMID 34710058, 2021). "Elucidating how metabolic sensors, such as HIF-1α, GLUT1, SIRT1, and AMPK, influence NK cell function in COVID-19 will enhance our understanding of disease pathogenesis and serve as a basis for novel therapeutic approaches in patients with COVID-19." (PMID 40927375, 2025). "It is conceivable that in the course of COVID-19 progression and stalling of NAD+ flux due to acute NAD+ depletion, less NAM will be liberated and processed by NNMT, leading to SIRT1 degradation and activation of KP." (PMID 35457123, 2022). "Thus, the use of SIRT1 activators, such as RES, or directly of NRF2 leads to an improvement in the pathophysiology of COVID-19." (PMID 35458574, 2022). "When not inhibited by TIMP-3, due to low SIRT1 activity-mediated TIMP-3 reduction, ADAM17 causes the release of TNF-α and IL6 and contributes to inflammation and possibly to the development of an uncontrolled hyperinflammatory response in COVID-19." (PMID 35457123, 2022). "If ADAM17 expression is not downregulated by SIRT1, TNF-α and IL-6 are released, resulting in an uncontrolled hyperinflammatory response as may happen with COVID-19." (PMID 35458574, 2022).
subarachnoid hemorrhage (24 papers, 2016 to 2025). A serious neurological disorder characterized by intracranial hemorrhage into the subarachnoid space. "In subarachnoid hemorrhage injury, SIRT1 facilitates M2 microglial polarization by suppressing ROS-mediated NLRP3 inflammasome activation, thus alleviates early brain injury." (PMID 38745316, 2024). "Our study elucidates that PD significantly ameliorates early brain injury following subarachnoid hemorrhage through the upregulation of SIRT1, leading to the suppression of endoplasmic reticulum stress." (PMID 39295935, 2024). "Sirt1 agonist can ameliorate subarachnoid hemorrhage injury via promoting M2 microglia polarization." (PMID 37650573, 2023). "In one research on subarachnoid hemorrhage, fucoxanthin reduced oxidative damage through a Sirt1-dependent pathway." (PMID 35126819, 2022). "Further, oleanolic acid prevented rat model from subarachnoid hemorrhage by SIRT1-modulated HMGB1 deacetylation." (PMID 34906140, 2021). "Resveratrol treatment enhances neuronal survival and reduces caspase-3 mediated apoptosis via SIRT1 activation in subarachnoid hemorrhage experimental rat model." (PMID 33737560, 2021). "In the subarachnoid hemorrhage rat model, Sirtinol treatment lowered SIRT1 expression, which further induced damage of the blood-brain barrier and neurological ability." (PMID 34650436, 2021). "Numerous studies have demonstrated that SIRT1 ameliorate neurodegenerative disease, such as AD 55, PD 56, subarachnoid hemorrhage 57, which reveal that SIRT1 delays senescence in the brain." (PMID 32132865, 2020). "Several investigators pointed out experimental traumatic brain injury (TBI) or subarachnoid hemorrhage induced oxidative stress and SIRT1 alteration in injured rats." (PMID 28706491, 2017). "The aim of this study was to investigate the change of SIRT1 in the brain after subarachnoid hemorrhage (SAH) and its role on SAH-induced early brain injury (EBI)." (PMID 27735947, 2016). "Resveratrol stimulates autophagy through the AMPK/SIRT1 signaling pathway, inhibiting the release of pro-inflammatory cytokines and neuronal apoptosis, thereby uncovering a novel molecular mechanism for its protective effect in subarachnoid hemorrhage." (PMID 37779164, 2024). "Modulating SIRT1 may therefore represent a promising therapeutic target for effectively reducing brain edema subsequent to subarachnoid hemorrhage." (PMID 37779164, 2024). "HMGB1/NF-kB pathway also might be downstream of SIRT1 to inhibit microglia activation and proinflammatory cytokines release in subarachnoid hemorrhage rats and LPS treated BV2 cells." (PMID 36111151, 2022). "Thus, for subarachnoid hemorrhage, a validated potent SIRT1 activator should be tested as a potential treatment." (PMID 34650436, 2021). "Moreover, recent studies have shown that SIRT1 activation protects against early brain injury after experimental subarachnoidal hemorrhage in rats." (PMID 30029514, 2018). "experimentally demonstrated that activation of sirtuin 1 (SIRT1), a sirtuin family member, suppresses NLRP3 inflammasome signaling in microglia during subarachnoid hemorrhage (SAH)." (PMID 40083546, 2025). "SRT1720, an agonist of Sirt1, can improve cell viability, promote M2 microglia polarization, suppress inflammatory response and inhibit oxidative damage via modulation of ROS-mediated NLRP3 inflammasome signaling after subarachnoid hemorrhage." (PMID 36725745, 2023).
brain injury (23 papers, 2017 to 2026). Acute and chronic (see also brain INJURIES, CHRONIC) injuries to the brain, including the cerebral hemispheres, CEREBELLUM, and brain STEM. "Previous studies have demonstrated that pharmacological promotion of SIRT1/VEGF signaling contributes to angiogenesis following ischemic brain injury." (PMID 40290868, 2025). "Our study contributes to the understanding of how targeting SIRT1 can modulate ER stress responses, offering potential therapeutic strategies for brain injuries." (PMID 39295935, 2024). "Our findings align with and extend the existing research on the neuroprotective effects of antioxidants and the role of SIRT1 in brain injuries." (PMID 39295935, 2024). "In an experimental traumatic brain injury study, Omega-3 polyunsaturated fatty acid alleviated the inflammation by modulating microglia polarization through SIRT1-modulated deacetylation of the HMGB1/NF-κB pathway." (PMID 34906140, 2021). "A previous study showed that increasing SIRT1 activity promoted the transformation of M1 microglia to the M2 phenotype and reduced the neuroinflammatory response after traumatic brain injury." (PMID 34975410, 2021). "It has been reported that interleukin‐17A and IL‐17A receptor IL‐17RA/(C/EBPβ)/SIRT1 signaling pathway enhances reactive astrogliosis after brain injuries." (PMID 31020769, 2019). "Although SIRT1 enhances Nrf2 expression to exert neuroprotective effects in traumatic brain injury, the role of SIRT1/Nrf2/GPx4 signal transduction in ferroptosis during HIBI remains unclear." (PMID 36184790, 2022). "Both beneficial and detrimental roles of SIRT1 expression have been described in astrocytes: For the former, overexpression of SIRT1 attenuates astrocyte activation in vitro and improves neurobehavioral function after brain injury." (PMID 36136587, 2022). "In this study, we found that increased Sirt1 expression could attenuate the astrocyte activation and improve the neurobehavioral function after brain injury, the mechanism of which may be related to effects of Sirt1 on mitochondrial function in astrocytes." (PMID 28356158, 2017). "In addition, berberine plays a protective role in brain trauma by regulating SIRT1 signal." (PMID 37483428, 2023). "In a mice model of repetitive mild traumatic brain injury (TBI), saffron extract was proved to attenuate the NOD-like receptors family pyrin domain-containing 3 (NLRP3) inflammasome signaling activation via the enhanced expression of SIRT1 in neuronal cells." (PMID 40806702, 2025). "The results of this study suggest that ω-3 PUFA supplementation attenuates the inflammatory response by modulating microglial polarization through SIRT1-mediated deacetylation of the HMGB1/NF-κB pathway, leading to neuroprotective effects following experimental traumatic brain injury." (PMID 29678169, 2018).